ESR1 (estrogen receptor 1)
Diseases named in the same sentence as ESR1 in open-access papers (continued):
Sharing a sentence is not in itself a finding about the gene and the disease.
sarcopenia (14 papers, 2015 to 2025). Progressive decline in muscle mass due to aging which results in decreased functional capacity of muscles. "Using the MTA‐MO method, we identified 639 gene targets, and by analysing PPIs and querying public databases, we narrowed this list down to seven potential hub genes associated with sarcopenia (ESR1, ATM, CDC42, EP300, PIK3CA, EGF and PTK2B)." (PMID 40045692, 2025). "Applying MTA-MO to multi-omics data identified seven potential hub genes associated with sarcopenia: ESR1, ATM, CDC42, EP300, PIK3CA, EGF, and PTK2B." (PMID 41303670, 2025). "The current study also identified the ESR1 rs4870044 T allele as a risk factor, with 2.5-fold higher risk of sarcopenia in T-allele carriers compared to CC homozygotes." (PMID 32076017, 2020). "This study analyzed 24 SNPs but found that only 4 SNPs (FTO rs9939609, ESR1 rs4870044, NOS3 rs1799983, and TRHR rs7832552) were significantly associated with sarcopenia." (PMID 40428823, 2025). "An remarked decease of ESR1 has also been observed in post‐menopause, which significantly contributed to muscle atrophy, sarcopenia and lipid abnormality." (PMID 39875775, 2025). "A previous study on genetic markers for sarcopenia identified the loci near FTO, ESR1, NOS3, KLF5, and HLA-DQA1 to be associated with physical phenotypes, such as low handgrip strength and decreased LBM24–26." (PMID 35241739, 2022). "It should be noted that the SNPs showing associations in the present study (ACTN3 rs1815739, MTHFR rs1801131, and MTHFR rs1537516) are different from our previous study that identified associations of FTO, TRHR, ESR1, and NOS3 gene variants with sarcopenia." (PMID 34768452, 2021). "Several studies have associated single-nucleotide polymorphisms (SNPs) with muscle mass and strength in the elderly, and recently our group found that sarcopenia in elderly women was associated with polymorphisms in FTO, TRHR, ESR1, and NOS3." (PMID 34768452, 2021). "Four SNPs were associated with the %SMM and SMI definitions of sarcopenia; FTO rs9939609, ESR1 rs4870044, NOS3 rs1799983 and TRHR rs7832552." (PMID 32076017, 2020). "Based on the %SMM definition, the SNPs FTO rs9939609, ESR1 rs4870044 and NOS3 rs1799983 were associated with sarcopenia." (PMID 32076017, 2020).
dementia (13 papers, 2018 to 2025). Loss of intellectual abilities interfering with an individual's social and occupational functions. "This study also highlights the protective role of ESR1_rs3844508 polymorphism in dementia predisposition." (PMID 39596595, 2024). "We performed an MDR analysis as well as a bioinformatic analysis to identify interactions between the genes GSTO1_rs4925, AGER_rs2070600, and ESR1_rs3844508 associated with susceptibility to dementia." (PMID 39596595, 2024). "In our study, we observed that the G allele of the ESR1 rs3844508 marker was associated with a lower risk for dementia." (PMID 39596595, 2024). "ESR1 polymorphisms are associated with the risk of developing dementia." (PMID 33423377, 2021). "On the other hand, with respect to ESR1 rs3844508 genotypes, the distribution of the AA genotype was not significantly different in both groups (46.0% in controls versus 55.2% in dementia, p = 0.061)." (PMID 39596595, 2024). "This is the first study that relates the genes that participate in the processes related to oxidative stress and the inflammatory response (GSTO, AGER and ESR1) in dementia." (PMID 39596595, 2024). "Associations of candidate genes with cognition are also exemplified by case–control and cohort studies linking polymorphisms in the estrogen receptor alpha (ER-α) gene, ESR1, to dementia and cognitive decline." (PMID 29608730, 2018).
acute myeloid leukemia (12 papers, 2008 to 2023). Acute myeloid leukemia (AML) is a group of neoplasms arising from precursor cells committed to the myeloid cell-line differentiation. "In contrast, the down-regulation of ESR1 is suggestive of better OS in acute myeloid leukemia (LAML), brain lower grade glioma (LGG), lung squamous cell carcinoma (LUSC) and stomach adenocarcinoma (STAD)." (PMID 34322374, 2021).
bone metastasis (12 papers, 2015 to 2026). Transfer of a neoplasm from its primary site to bones. "While mutations in ESR1 are rare in primary tumors (less than 1%) recently has been reported that the prevalence of ESR1 mutations is higher in diagnosed metastatic patients (6–55%), including in patients with bone metastasis." (PMID 39483629, 2021). "Low expression of VIM and RB1 (p = 0.020) but high ESR1 expression (p = 0.020) was identified in CTCs’ patients who had bone metastasis." (PMID 31817194, 2019). "In metastatic site-specific analyses, associations of ESR1 with liver metastasis and RICTOR with bone metastasis were significant, regardless of intrinsic subtypes." (PMID 34272397, 2021). "The associations of ESR1 mutations with liver metastasis and RICTOR mutations with bone metastasis were significant, irrespective of the intrinsic subtypes." (PMID 34272397, 2021).
cholangiocarcinoma (12 papers, 2009 to 2025). A carcinoma that arises from the intrahepatic biliary tree (intrahepatic cholangiocarcinoma) or from the junction, or adjacent to the junction, of the right and left hepatic ducts (hilar cholangiocarcinoma). "The ESR1 positive cases in lung, colon, and cholangiocellular carcinoma, and other cancer entities also refer to all variants found in the ESR1 LBD, most of which are currently specified as variants of unknown significance." (PMID 40282442, 2025). "Notable, GLY has shown estrogenic properties and the ability to induce the proliferation of estrogen-dependent MCF-7 human BC cells and ERalpha (ESR1)-positive cholangiocarcinoma cells." (PMID 40469091, 2025). "ESR1 significantly impacts the prognosis of iCCA patients and markedly suppresses cholangiocarcinoma cell proliferation, migration and invasion by inhibiting JAK/STAT3 signaling pathway." (PMID 33865377, 2021). "The results showed that the ESR1 expression level in the HCCC-9810 cell line was the lowest and that the RBE cell line was the highest among the four cholangiocarcinoma cell lines." (PMID 33865377, 2021). "TCGA-CHOL (Cholangiocarcinoma) shows upregulations of HTR3A (35.1-fold) and GPR35 (G Protein-Coupled Receptor 35) (33.9-fold), with downregulations in ADRA1A (−74.3-fold) and ESR1 (Estrogen Receptor 1) (−43.2-fold)." (PMID 39766077, 2024).
cognitive decline (12 papers, 2012 to 2026). "Furthermore, the relative ESR2/ESR1 expression ratio is increasingly appreciated as important in memory performance and cognitive decline with respect to age." (PMID 30635056, 2019).
endothelial dysfunction (12 papers, 2008 to 2024). In vascular diseases, endothelial dysfunction is a systemic pathological state of the endothelium (the inner lining of blood vessels) and can be broadly defined as an imbalance between vasodilating and vasoconstricting substances produced by (or acting on) the endothelium. "In contrast, in sPE, endometrial ESR1 and IHH are downregulated, decreasing PGR expression and leading to compromised decidualization, endothelial dysfunction, and local immune dysregulation." (PMID 34709177, 2021).
pituitary adenomas (12 papers, 2012 to 2025). "Total 158 gonadotropin-type pituitary adenoma tissue specimens were collected and the expression of ESR1 in gonadotropin-type pituitary adenoma and its association with the overall survival of patients were analyzed." (PMID 36605480, 2023). "Herein, the association of ESR1 expression and overall survival of patients with pituitary adenoma were analyzed." (PMID 36605480, 2023). "In summary, our immunohistochemical staining result from the specimen samples demonstrated that low-level ESR1 had longer progression-free survival (PFS) in pituitary adenoma patients." (PMID 36605480, 2023). "In this study, the expression level of ESR1 and the relationship of ESR1 and overall survival of patients with pituitary adenoma were investigated." (PMID 36605480, 2023). "The effect of fulvestrant and AZD9496 on the proliferation of ESR1-postive pituitary adenoma were investigated." (PMID 36605480, 2023). "Further studies showed that STAT5B was significantly positively correlated with ESR1 expression in pituitary adenoma." (PMID 36605480, 2023). "The expression of STAT5B was significantly positively correlated with ESR1 expression in the pituitary adenoma." (PMID 36605480, 2023). "In this study, we found the STAT5B is positively related to ESR1 expression in pituitary adenoma." (PMID 36605480, 2023). "Low-level ESR1 had longer progression-free survival (PFS) in pituitary adenoma patients." (PMID 36605480, 2023). "It suggests that STAT5B may be a key player in the ESR1-reuglated growth of pituitary adenoma." (PMID 36605480, 2023).
Pleural effusion (12 papers, 2008 to 2025). The presence of an excessive amount of fluid in the pleural cavity. "The presence of mutated ESR1 found in a patient with pleural effusion is consistent with what has been described in metastatic breast cancers." (PMID 37371673, 2023).
thyroid (12 papers, 2015 to 2025).
Arthritis (11 papers, 2010 to 2026). Inflammation of a joint. "Hormone receptors (AR and ESR1) are even more important players in the inflammatory process and can play a potent role in bone inflammatory diseases such as arthritis and bursitis, through the synthesis of steroid hormones (sex hormones and glucocorticoids) via the second messenger cAMP pathway." (PMID 35051095, 2021).
Hypercholesterolemia (11 papers, 2009 to 2024). An increased concentration of cholesterol in the blood. "In our study, we found an association between ESR1 long TA allele and hypercholesterolemia in young healthy subjects and it could represent a possible risk factor for developing metabolic disorder and cardiovascular disease." (PMID 19804633, 2009). "Further, association was also established between ESR1 and APOE genetic polymorphisms and hypercholesterolemia." (PMID 19804633, 2009).
hypospadias (11 papers, 2008 to 2025). Hypospadias is the displacement of the urethral meatus on the ventrum of the penis. "Various polymorphisms in ESR1 are associated with the risk of hypospadias, and ESR1 expression are also reported to be associated with hypospadias." (PMID 32515122, 2020). "But another three studies identified that ESR1 associated with significantly increased risk of hypospadias." (PMID 27247884, 2016). "Moreover, male mice with knockout of the genes encoding either ERα (Esr1) or aromatase (Cyp19a1) exhibit mild hypospadias." (PMID 41019341, 2025). "In addition, our findings suggests that genes encode for proteins interacting with ESR1 are enriched in hypospadias, indicating that ESR1 signaling plays an crucial role in prenatal penile development." (PMID 32515122, 2020). "In conclusion, our study provides evidence that SNP12 in ESR1 influence the risk of hypospadias." (PMID 27247884, 2016). "The results indicate that there is significant association between SNP12 in ESR1 and hypospadias." (PMID 27247884, 2016). "While Ar and Esr1 likely play a role in the severe hypospadias phenotypes observed postnatally in males exposed to 6 mg/kg bw/day of flutamide, it is probable that other molecular changes are also involved." (PMID 41019341, 2025). "Estrogen receptor α or Esr1 knockout mice develop mild hypospadias in adulthood, similar to estrogen exposed mice." (PMID 35846302, 2022). "Our findings suggest that AR and ESR1 signaling play a critical role in the development of mild and severe hypospadias using the gene expression profiling." (PMID 32515122, 2020). "In recent years, some studies have investigated the relationship between the SNP12 in ESR1 and hypospadias, but there exit inconsistency among all results." (PMID 27247884, 2016). "In recent years, estrogen receptor (ER) related gene with hypospadias is a new research hotspot, especially estrogen receptor α gene (ESR1)." (PMID 27247884, 2016). "The main excluded reason was duplication, reviews, non population-based studies or irrelevant to SNP12 in ESR1 and hypospadias." (PMID 27247884, 2016). "Our study provided preliminary evidence that the imbalance of AR and ESR1 signaling are present in hypospadias, which may affect the individual patient by various routes." (PMID 32515122, 2020). "Significant alterations in DNA methylation of sex hormone receptor genes (ESR1 and AR) and fibroblast growth factor (FGFR2 FGF8) may correlate with abnormal expression of these genes in patients with hypospadias." (PMID 39959693, 2025). "ESR1 SNPs and haplotypes influence the risk of hypospadias in nonHispanic white and Hispanic population, while variants in ESR2 are associated with hypospadias in the Swedish cohort." (PMID 31856834, 2019).
ovarian failure (11 papers, 2011 to 2026). "Therefore, down-regulation of fshr and mTOR signaling pathway in esr1 deficient zebrafish may be relevant to ovarian failure." (PMID 30319547, 2018). "On the other hand, by the age of 180 dpf, the IGF system and mTOR signaling pathway were comprehensively down-regulated in esr1 mutant zebrafish, accompanied with ovarian failure." (PMID 30319547, 2018). "In KGN cells modeling LPD and POF phenotypes, cellular experiments confirmed that BaP downregulated EGFR and ESR1 expression while upregulating STAT3 expression, thereby supporting the reliability of these targets in BaP-induced ovarian dysfunction." (PMID 41828455, 2026). "Estrogen receptor 1 (ESR1) and phosphatase and tensin homolog (PTEN) have been indicated as candidate genes for ovarian failure." (PMID 35316486, 2022).
autism (10 papers, 2013 to 2025). Persistent deficits in social interaction and communication and interaction as well as a markedly restricted repertoire of activity and interest as well as repetitive patterns of behavior. "ERα-knock-out mice exhibit social deficits, and a single-nucleotide polymorphism was reported to correlate with severity in social interaction deficits in a group of children with autism, although ESR1 is not considered a high confidence risk gene for ASD." (PMID 40623833, 2025). "Interestingly, in a genetic association study, Chakrabarti and colleagues identified variations in the ARNT2 gene, ESR1, ESR2 and also CYP19A1 to be associated with ASC diagnosis and/or autism traits in the general population." (PMID 26066795, 2015).
benign breast disease (10 papers, 2006 to 2024). "Except for breast tissues, methylated ESR1 levels in serum or plasma were also investigated and found to be higher in BC than in healthy control and benign breast disease." (PMID 37881785, 2023).
female infertility (10 papers, 2015 to 2025). Diminished or absent ability of a female to achieve conception. "We previously reported that conditional genetic ablation of Esr1 (estrogen receptor α) in the epithelial cells of the female reproductive tract (Wnt7aCre/+;Esr1f/f) causes female infertility, partly due to a drastic reduction in the number of motile sperm entering the oviduct." (PMID 28414719, 2017). "ESR1 has been involved in the genetic variation of female infertility, and Sparta is an acrosomal protein in sperm and related to genetic mutation in sperm." (PMID 34639162, 2021).
Fibroadenoma (10 papers, 2011 to 2025). A benign tumor of the breast characterized by the presence of stromal and epithelial elements. "We have identified the methylation of five cancer-related CpG islands in the giant fibroadenoma tissue: ESR1, MGMT, WT-1, BRCA2 and CD44." (PMID 22011321, 2011).
idiopathic scoliosis (10 papers, 2013 to 2026). A scoliosis with no known cause. "Our previous studies focused on the ESR2 gene polymorphism in patients with idiopathic scoliosis, as well as on methylation of both ESR1 and ESR2 genes." (PMID 35627124, 2022). "XbaI single nucleotide polymorphism (SNP) (A/G rs934099) in estrogen receptor 1 gene (ESR1) was described to be associated with curve severity in Japanese idiopathic scoliosis (IS) patients and in Chinese patients with both curve severity and predisposition to IS." (PMID 24155906, 2013). "A recent cross-sectional study revealed that some ESR1 and ESR2 variants were associated with the occurrence risk of idiopathic scoliosis." (PMID 34064195, 2021). "The DNA methylation level of ESR1 regulatory regions is specific to the muscle tissue localization in patients with idiopathic scoliosis." (PMID 34064195, 2021). "We have already published on ESR1 and ESR2 gene polymorphisms association with idiopathic scoliosis occurrence and severity." (PMID 27045366, 2016). "Moreover, many promising polymorphisms within different genes (including ESR1, ESR2) have been identified for the occurrence and curve progression of idiopathic scoliosis." (PMID 35627124, 2022). "In conclusion, the ESR1 and ESR2 presence was confirmed in skeletal paravertebral muscles of patients with idiopathic scoliosis." (PMID 35627124, 2022). "The study aimed to detect the presence and assess the expression levels of the estrogen receptors type 1 (ESR1) and type 2 (ESR2) within paravertebral skeletal muscles of female patients with idiopathic scoliosis (IS) in relation to phenotype parameters." (PMID 35627124, 2022). "Using the reverse transcription followed by polymerase chain reaction, the western blot, and immunohistochemistry techniques, the estrogen receptors ESR1 and ESR2 presence were confirmed in the muscular cells of the paraspinal skeletal muscles in a cohort of children with idiopathic scoliosis." (PMID 35627124, 2022).
metastasis (10 papers, 2015 to 2023). The spread or migration of cancer cells from one part of the body (where they first appeared) to another. "In bone metastasis, 14% of ER‐positive cases were found to be ESR1‐mutated." (PMID 34779146, 2021). "The odds of a sample with visceral metastasis having an ESR1 mutation is 4.66 times the odds of a sample of nonvisceral metastasis having an ESR1 mutation (95% CI: 1.13–19.27; p value = 0.0333)." (PMID 31511774, 2019).
ovarian endometriosis (10 papers, 2012 to 2025). A non-neoplastic disorder characterized by the growth of endometrial tissue in the ovaries. "Dys-regulation of three (CLOCK, ESR1, and MYC) major transcription factors appeared to be significant causative factors in the pathogenesis of ovarian endometriosis." (PMID 23006437, 2012). "We performed RWR algorithm analyses of the ceRNA network using four validated ovarian endometriosis-related genes (ESR1, SNCG, PTCH1, and MUC1) as seed nodes, prioritizing ovarian endometriosis-related lncRNAs, and we also performed permutation tests." (PMID 33584822, 2021). "Ten paraffin-embedded ovarian endometriosis samples were screened for germ cell-specific proteins DDX4 (VASA) and IFITM3, and its relation with stem cell marker OCT4, proliferation marker PCNA and estrogen receptor alpha (ESR1), by immunohistochemistry, immunofluorescence and PCR." (PMID 26446766, 2015).